ANKRD1 (ankyrin repeat domain 1)
Diseases named in the same sentence as ANKRD1 in open-access papers (continued):
Sharing a sentence is not in itself a finding about the gene and the disease.
breast cancer (14 papers, 2015 to 2025). A primary or metastatic malignant neoplasm involving the breast. "Our results show that the expression of ANKRD1 has significant clinical diagnostic significance in breast cancer metastasis." (PMID 39409926, 2024). "Our findings show that ANKRD1 is a potential therapeutic target and a diagnostic marker for breast cancer metastasis." (PMID 39409926, 2024). "In conclusion, we found that ANKRD1 is associated with breast cancer metastasis." (PMID 39409926, 2024). "We investigated whether the underlying mechanism(s) of ANKRD1-mediated breast cancer migration is correlated with epithelial mesenchymal transition (EMT), migration, adhesion and cancer-associated fibroblasts (CAFs)." (PMID 39409926, 2024). "Validated down-regulated genes include NPC2 involved in the negative regulation of MAPK, TSPAN8 involved in tumor progression and metastasis, ANKRD1 mainly expressed in MDA-MB231 breast cancer cell lines and linked to treatment-resistance in breast cancer, and FST involved in metastasis suppression." (PMID 34680207, 2021). "We performed overexpression of ANKRD1 in non-metastatic breast cancer cells (MCF7 and T47D) and knockdown of ANKRD1 in highly metastatic breast cancer cells (LM2)." (PMID 39409926, 2024). "We studied the downstream pathway of ANKRD1 and found that ANKRD1 promotes breast cancer cell migration and metastasis through the NF-κB and MAGE-A6 pathway." (PMID 39409926, 2024). "Breast cancer: in breast cancer, Ankrd1 not only mediates resistance to drugs like phenylbutyrate but also plays a critical role in the epithelial-mesenchymal transition (EMT)." (PMID 39420247, 2024). "Most of all, ANKRD1 was significantly downregulated in the breast cancer cells that had low metastatic capacity." (PMID 39409926, 2024). "In this study, we demonstrate that the ANKRD1 gene or CARP protein is significantly upregulated in high-grade human breast cancer tissues compared to low-grade tissues." (PMID 39409926, 2024). "Data from microarray showed high expression of ANKRD1 in highly metastatic breast cancer cells compared to low metastatic breast cancer cells." (PMID 39409926, 2024). "In this study, we found increased levels of ANKRD1 in highly metastatic breast cancer cell lines and human tissues of high-grade breast cancer." (PMID 39409926, 2024). "Our study suggests that ANKRD1 promotes metastasis of breast cancer by activating NF-κB as well as MAGE-A6 signaling." (PMID 39409926, 2024). "In this study, we have identified ANKRD1 as a potential biomarker of poor-prognosis breast cancer metastasis and elucidated its downstream pathway in breast cancer cells." (PMID 39409926, 2024). "Our results are in agreement with a previous work demonstrating that Ankrd1 is upregulated in mammary tumours in a Wnt/β-Catenin-dependent manner." (PMID 27790377, 2016). "Among the identified Setdb1 genomic targets, Ankrd1 appeared of particular interest due to its involvement in myogenesis and its Wnt/β-Catenin-dependent induction in mammary tumours." (PMID 27790377, 2016). "In breast cancer, Ankrd1 expression is positively regulated by Snail, which induces EMT." (PMID 40362467, 2025). "Furthermore, the survival data from the Kaplan–Meier survival analysis of distant metastasis-free survival (DMFS) breast cancer patients with metastatic disease suggested that breast cancer patients with higher ANKRD1 expression have lower survival rates." (PMID 39409926, 2024). "In this study, we propose that ANKRD1 promotes metastasis of breast cancer." (PMID 39409926, 2024). "Our findings suggest that ANKRD1 may play a significant role in breast cancer migration and metastasis by regulating the NF-κB-MAGE-A6 cascade." (PMID 39409926, 2024). "In this study, we aimed to investigate the role of ANKRD1 in breast cancer metastasis." (PMID 39409926, 2024).
breast cancer (continued). "However, our recent analysis based on the TCGA database showed decreased DNA methylation in the promoter region of Ankrd1 in patients with breast cancer, lung cancer, or pancreatic cancer." (PMID 39420247, 2024). "Moreover, H&E results showed lower liver metastatic potential (cancer area) of LM2-ANKRD1 knockdown cells compared to control cells, suggesting a role of ANKRD1 in breast cancer metastasis." (PMID 39409926, 2024). "To confirm whether ANKRD1 is highly expressed in highly metastatic cells compared to non-metastatic cells, we performed immunohistochemical staining (IHC) of ANKRD1 in the breast cancer tissue array." (PMID 39409926, 2024). "The relevance of the ANKRD1-NF-κB-MAGE-A6 axis in breast cancer is its pro-metastatic role." (PMID 39409926, 2024). "Collectively, these results demonstrated that ANKRD1 expression level correlated with higher grade and aggressiveness of breast cancer and suggested that ANKRD1 may play a significant role in breast cancer progression and metastasis." (PMID 39409926, 2024). "Furthermore, the in vivo mouse model and immunohistochemistry using a human breast cancer tissue array showed higher expression of ANKRD1 in high-grade breast cancer compared to low-grade breast cancer." (PMID 39409926, 2024). "ANKRD1 is a novel determinant of cisplatin resistance in ovarian and breast cancers." (PMID 26646320, 2016). "These in vitro results suggested that ANKRD1 may trigger breast cancer migration through EMT." (PMID 39409926, 2024). "To confirm the modulation of MAGE-A6 in ANKRD1-mediated breast cancer metastasis, we performed immunoblotting of the MAGE-A6 protein in ANKRD1-overexpressing cells." (PMID 39409926, 2024). "Our studies showed that ANKRD1 allows the activation of IκKα–NF-κB-MAGE-A6, leading to breast cancer metastasis." (PMID 39409926, 2024). "Accordingly, siNUAK2 blocked YAP/TAZ transcriptional activity as assessed using a TEAD-luciferase reporter and by measuring expression of the endogenous target genes, ANKRD1 and CTGF, in two breast cancer lines." (PMID 30158528, 2018). "We also analyzed the expression of ANKRD1 and YAP1 in different human cancer cell lines, including lung cancer (H322, A549 and A427), prostate cancer (LNCaP and PC-3), breast cancer (MCF7) and skin cancer (MeWo and Sk-Mel-28)." (PMID 29179447, 2017). "Overexpression of Ankrd1 was related to EMT promotion in lung and breast cancers." (PMID 40362467, 2025). "In previous work, we screened the differential gene expression between non-metastatic and highly metastatic breast cancer cell lines by using cDNA microarray and found that ANKRD1 was upregulated in the highly metastatic cell lines (unpublished data)." (PMID 39409926, 2024). "Importantly, MAP3K3 knockdown reduced YAP expression in palbociclib-resistant breast cancer cells and downregulated the expression of the YAP target genes CTGF, CYR61, and ANKRD1." (PMID 38622197, 2024). "AGAP2-AS1 could be promising predictive biomarker and therapeutic target for HER-2+ breast cancer patients, and AGAP2-AS1 regulated the proliferation and migration of pancreatic cancer partly through suppressing ANKRD1 and ANGPTL4." (PMID 36911393, 2023). "Therefore, ANKRD1 and MAGE-A6 may be used as targets for anti-metastatic therapy of breast cancer in the future." (PMID 39409926, 2024). "However, the association between low survival rates and high expression of ANKRD1 does not correlate with any specific subtype of breast cancer." (PMID 39409926, 2024). "ANKRD1 was found to be highly expressed in the MDA-MB-231 and MDA-LM-2 highly metastatic breast cancer cell lines compared to the non-metastatic breast cancer cell lines (MCF-7, ZR-75-30, T47D) and normal breast cancer cells (MCF-10A)." (PMID 39409926, 2024). "To determine the involvement of ANKRD1 in the migration of breast cancer cells, we established stable MCF7-ANKRD1-overexpressing cell lines (OE) by transfecting lentivirus vector into non-metastatic breast cancer cells (MCF-7)." (PMID 39409926, 2024).
cardiac hypertrophy (12 papers, 2012 to 2025). "Further research underscores the complexity of Ankrd1's role in cardiac hypertrophy, including its interaction with the calcineurin-NFAT signaling pathway and the MAPK/ERK and TGF-β/Smad3 pathways, which are crucial in mediating hypertrophic responses." (PMID 39420247, 2024). "The Ankrd1’s upregulation has been reported in various cardiac hypertrophy models in vitro and in vivo, including those induced by transverse aortic constriction (TAC), hypertensive stimuli, and hormonal influences like isoprenaline and angiotensin II." (PMID 39420247, 2024). "Given the importance of ANKRD1 in regulating fibrosis and cardiac hypertrophy, further studies are required to assess if its induction in response to low Fli1 in Mo/Mø contributes to their fibrogenic effects." (PMID 32508810, 2020). "Overexpressed mouse Ankrd1 is indeed involved in inhibition of cardiac hypertrophy and development of fibrosis in response to pressure overload- and isoproterenol-induced cardiac hypertrophy." (PMID 31428229, 2019). "As discussed in previous sections, ANKRD1 was shown to play important roles in various pathological pathways that lead to cardiac hypertrophy and fibrosis, as well as apoptosis." (PMID 28672880, 2017). "The attenuation of cardiac hypertrophy by ANKRD1 was also found to involve the inhibition of ERK and TGF-β/Smads signaling pathways by ANKRD1 in the same report." (PMID 28672880, 2017). "In adult cardiac muscle ANKRD1 expression is developmentally downregulated but was reported to increase in animal models of cardiac hypertrophy and human patients with various forms of cardiomyopathy leading to heart failure." (PMID 26973524, 2016). "This study provided both in vitro and in vivo evidence that myocardial overexpression of Ankrd1/CARP promotes cardiac hypertrophy." (PMID 25089522, 2014). "Furthermore, the knockdown of Ankrd1 attenuated phenylephrine-induced cardiac hypertrophy by inhibiting ANKRD1/ERK/GATA4 (involved in regulating cardiomyocyte growth) complex formation in the sarcomere and its nuclear translocation." (PMID 36551326, 2022). "However, on the other hand, ANKRD1 has also been shown to protect against cardiac hypertrophy, cardiac fibrosis and display anti-apoptotic properties." (PMID 28672880, 2017). "Accordingly, ANKRD1 has been observed to be highly induced in cardiac hypertrophy." (PMID 28672880, 2017). "It has been suggested that induction of ANKRD1 is an adaptive and protective response against various stresses as ANKRD1-over-expressing transgenic mice displayed markedly decreased cardiac hypertrophy in response to pressure overload or continuous isoproterenol infusion compared to wild type mice." (PMID 28672880, 2017). "Furthermore, myocardial overexpression of Ankrd1 was found to promote TAC-induced cardiac hypertrophy." (PMID 25089522, 2014). "One week after TAC, we noted that myocardial transduction of AAV-sh-Ankrd1 could inhibit cardiac hypertrophy evidenced by that the HW/BW ratio was significantly smaller in AAV-sh-Ankrd1-TAC mice than in the scramble-TAC mice." (PMID 25089522, 2014). "Similar to the genes for natriuretic peptides and β-myosin heavy chain (β-MHC), the gene for CARP (termed ankyrin repeat domain 1: Ankrd1) was also identified as a fetal gene, expression of which is augmented in both animals and humans with cardiac hypertrophy and heart failure (HF)." (PMID 25089522, 2014). "However, genetic ablation of Ankrd1 prevents DCM phenotype development in a genetic model of DCM and attenuates chemically induced cardiac hypertrophy." (PMID 36551326, 2022). "Similarly, ANKRD1 was previously named cardiac ankyrin repeat protein (CARP) and has been proposed as a marker of cardiac hypertrophy due to its increased expression in three distinct models of cardiac hypertrophy in rats." (PMID 31557856, 2019).
cardiac hypertrophy (continued). "For example, the Ankrd1 gene, a marker of cardiac hypertrophy that is markedly upregulated, had little or no detectable promoter H3K23Pr peak, while its mRNA exhibited the highest fold increase after pressure overload, which was equivalent in the hearts of mice on BCAA control and BCAA-free diets." (PMID 37669116, 2023). "Although there is clinical evidence that Ankrd1 mutations are involved in the pathogenesis of hypertrophic and dilated cardiomyopathy, there is no consensus about whether CARP enhances or attenuates cardiac hypertrophy." (PMID 25089522, 2014).
lung carcinoma (11 papers, 2017 to 2025). "In lung cancer, cell lines with high Ankrd1 expression exhibited higher migration abilities, and Ankrd1 expression was regulated by the EMT marker ZEB1." (PMID 40362467, 2025). "The presence of Ankrd1 thus represents a significant challenge in the management of lung cancer, as it impairs the response to therapies that are otherwise effective in targeting specific oncogenic drivers in this disease." (PMID 39420247, 2024). "ANKRD1 is a universal tumor suppressor that plays a role in many cancers through positive regulation of apoptosis, such as pancreatic and lung cancers." (PMID 37702613, 2023). "A remarkable number of papers have demonstrated that Ankrd1 is involved in the progression of cancers such as those afflicting ovaries, breast, pancreas and in the chemoresistance of lung cancer." (PMID 33419058, 2021). "Our result revealed that ATF3 and ANKRD1 were downregulated in malignant cells and mice primary lung cancer tissues induced by PAHs." (PMID 34497759, 2021). "Lung cancer: similarly, in lung cancer, Ankrd1 corelated with the resistance to targeted therapies." (PMID 39420247, 2024). "Similarly, another study focusing on EGFR-mutant lung cancer observed elevated levels of ANKRD1 in tumor tissues that had failed EGFR-TKI therapy." (PMID 38438492, 2024). "Long-term exposure of lung cancer cells to EGFR-TKIs may lead to accumulation of ANKRD1 protein." (PMID 30291293, 2018). "Moreover, we also observed that ANKRD1 and ATF3, as the target genes of EGR1, were significantly downregulated in malignant transformed cells and mice lung cancer tissues." (PMID 34497759, 2021).
pancreatic cancer (9 papers, 2017 to 2025). "Epigenetic inhibition of Ankrd1 correlates with the progression of pancreatic cancer." (PMID 40362467, 2025). "A previous study demonstrated that ANKRD1 could be inhibited by lncRNA, resulting in the promotion of pancreatic cancer proliferation and metastasis." (PMID 34497759, 2021). "A study reported that ANKRD1 acts through the YAP pathway to promote cell mobility, tumorigenesis, and invasion in pancreatic cancer." (PMID 39409926, 2024).
hypertrophic cardiomyopathy (5 papers, 2014 to 2024). "Missense mutations in the Ankrd1 gene have recently been identified as the cause of dilated and hypertrophic cardiomyopathy in humans." (PMID 38438525, 2024). "Likewise, CARP is induced in patients with hypertrophic, dilated, ischemic, and arrhythmogenic right ventricular cardiomyopathy and missense mutations in the Ankrd1 gene were recently shown to be causative for human dilated and hypertrophic cardiomyopathy." (PMID 24736439, 2014).
liver fibrosis (5 papers, 2017 to 2026). "Ankrd1 has been mentioned in several organ fibrosis, including cardiac fibrosis, hepatic fibrosis, and renal fibrosis." (PMID 39420247, 2024). "The activated hepatic stellate cells (HSCs) isolated from CCl4-induced and common bile duct ligation (CBDL)-induced liver fibrosis model increased Ankrd1 expression, which was completely dependent on YAP." (PMID 39420247, 2024). "A previous report has shown that ANKRD1 was upregulated in a CCl4-induced liver injury mouse model, suggesting that ANKRD1 may also play a role in the development of liver fibrosis in BA." (PMID 33553074, 2020).
muscular dystrophy (5 papers, 2008 to 2022). Muscular dystrophy (MD) refers to a group of more than 30 genetic diseases characterized by progressive weakness and degeneration of the skeletal muscles that control movement. "ANKRD1 is elevated following exercise, during muscle regeneration, tissue injury, and several congenital myopathies and muscular dystrophies." (PMID 27486743, 2016). "Judged from the studies in which Ankrd1 is differentially expressed, Ankrd1 could be the most robust marker for muscular dystrophy with ongoing regeneration." (PMID 18577208, 2008). "ANKRD1 and MYOZ2 were found to be related to muscular dystrophy." (PMID 21637832, 2011).
myocardial infarction (5 papers, 2022 to 2025). Gross necrosis of the myocardium, as a result of interruption of the blood supply to the area, as in coronary thrombosis. "Similarly, the mouse-Geneformer model predicted that deletion of genes Nppb, Ankrd1, and Myh7 from myocardial infarction cells would also lead to a transition towards a normal state." (PMID 40106407, 2025). "The mouse-Geneformer similarly indicated that activation of Ankrd1 and deletion of Myh7 could lead to a comparable transition from normal heart cells towards myocardial infarction cells." (PMID 40106407, 2025). "Additionally, Ankrd1 has been identified as a biomarker in the infarct boundary zones, highlighting its potential utility in defining the extent of myocardial infarction." (PMID 39420247, 2024). "Conversely, human-Geneformer model predicted that deleting ANKRD1 and NPPB from myocardial infarction cells would revert them to a more normal cellular state." (PMID 40106407, 2025). "The original human-Geneformer predicted that activation of NPPB and ANKRD1, as well as deletion of MYH7, could drive normal heart cells towards myocardial infarction state." (PMID 40106407, 2025).
arrhythmogenic right ventricular cardiomyopathy (4 papers, 2012 to 2024). "Ankrd1’s involvement extends to arrhythmogenic right ventricular cardiomyopathy (ARVC), where abnormal increases in Ankrd1 expression have been observed." (PMID 39420247, 2024).
lupus nephritis (4 papers, 2013 to 2024). Glomerulonephritis in the context of systemic lupus erythematosus. "Other genes of interest include the TWEAK receptor FN14, whose expression on intrinsic renal cells promotes glomerulonephritis, ANKRD1, which is associated with proteinuria in SLE nephritis, TLRs 2 and 13, and several proteinase inhibitors of the Serpin family involved in the coagulation pathway." (PMID 24167575, 2013). "Interestingly, the level of ANKRD1 protein in podocytes of patients with lupus nephritis correlates with the severity of proteinuria." (PMID 39285846, 2024). "Although ANKRD1 was initially reported to be upregulated in podocytes in various human kidney diseases, including crescentic glomerulonephritis, diabetic nephropathy, and lupus nephritis, a recent report showed ANKRD1’s involvement in vascular injury." (PMID 34244474, 2021). "Ankrd1 was notably present in crescentic glomerulonephritis, diabetic nephropathy, and lupus nephritis, yet absent in endocapillary glomerulonephritis, minimal change disease, and normal kidneys." (PMID 39420247, 2024). "Notably, Ankrd1 levels were higher in lupus nephritis cases with nephrotic syndrome compared to those without." (PMID 39420247, 2024).
Atrophy (3 papers, 2015 to 2019). Any weakening or degeneration, especially through lack of use. "Moreover, a switch towards fast-twitch fibres has been reported in models of atrophy in association with up-regulation of ANKRD1." (PMID 25567521, 2015). "However, MAFbx and Ankrd1 were not significantly upregulated and the fold increase in MuRF1 and Foxo3 was low, indicating that this model is incomplete when compared to atrophy modeling in vivo." (PMID 30906768, 2019).